PHLDA1 (pleckstrin homology like domain family A member 1)
Diseases named in the same sentence as PHLDA1 in open-access papers (continued):
Sharing a sentence is not in itself a finding about the gene and the disease.
tumor (continued). "PHLDA1 is known to act as a tumor suppressor by inhibiting AKT signaling pathway and a decreased expression of it has been confirmed in various type of cancers like ovarian and breast." (PMID 37749575, 2023). "While in other studies, PHLDA1 overexpression promoted cell proliferation and tumor growth via Ras/Raf/Mek/Erk signaling pathway, indicating its complex function in tumor genesis and drug resistance." (PMID 37291676, 2023). "Whilst PMA served as a useful tool to highlight the role of PKC/MAPK signalling in the regulation of PHLDA1 levels, its well-documented tumour-promoting effects limited its use in our studies." (PMID 37047202, 2023). "First, PHLDA1 was positively correlated with the infiltration levels of a variety of immunocompetent tumor-infiltrating cells, including Act CD4, CD56dim, and Act DC, and 23 types of immune promoters, including IL6, NT5E, and TNFSF9." (PMID 36142223, 2022). "Again, the enhanced anti-tumor efficacy of this combination therapy was abrogated by siRNA-mediated PHLDA1/2 depletion and the consequent AKT activation." (PMID 35831322, 2022). "The promoter methylation levels of PHLDA1/3 in the tumor tissues of patients were significantly higher than those in the paracancerous tissues (p = 4.506 × 10−2/p = 6.353 × 10−5)." (PMID 36142223, 2022). "For example, PHLDA1 was positively correlated with the infiltration levels of a variety of immunocompetent tumor-infiltrating cells, including Act CD4, CD56dim, and Act DC and 23 types of immune promoters, including IL6, NT5E, and TNFSF9." (PMID 36142223, 2022). "Expression of PHLDA1 was found to be reduced in primary and metastatic melanomas compared with benign melanocytic nevi, resulted in resistance of the tumor cells to apoptosis." (PMID 34405011, 2021). "We performed RT-qPCR analysis on 40 sOvCa and 27 normal specimens and found significantly higher PHLDA1 mRNA levels in the tumor tissues compared with normal tissues (P=0.0007)." (PMID 34405011, 2021). "PHLDA1 has been shown to act as an oncogene or a tumor-suppressor depending on what tissues are involved as reviewed previously." (PMID 32429563, 2020). "In all cases, patients treated with an RTK inhibitor exhibited reduced PHLDA1, suggesting that PHLDA1 downregulation occurs in response to RTK inhibition in multiple tumor types." (PMID 29490281, 2018). "This suggests robust expression of PHLDA1 in mammary epithelium, downregulation of PHLDA1 in tumor versus adjacent normal tissue suggestive of a putative tumor suppressor role and also regulation by ErbB2 as suggested by the profiling studies as well." (PMID 25238247, 2014). "Moreover, the high expression of PHLDA1 in CAFs and its significant correlation with poor prognosis indicate that it plays an important role in modulating the tumor microenvironment." (PMID 40688078, 2025). "By applying Perturb-DBiT to CAF populations, researchers could uncover PHLDA1’s spatially resolved downstream effectors and identify context‐dependent interactions between CAFs and tumor cells in situ." (PMID 40688078, 2025). "We propose that PHLDA1+ CAFs contribute to tumor growth and immune modulation by activating protumorigenic signaling pathways—such as PI3K/Akt, TGF-β, and KRAS—which, in turn, may impact patient prognosis and therapeutic response." (PMID 40688078, 2025). "Moreover, PHLDA1 was shown to be expressed differently in tumor and adjuvant tumor tissues by further western blot and IHC staining." (PMID 40688078, 2025). "The literature broadly describes the tumor suppressor functions of PHLDA1." (PMID 39630301, 2025). "Although previous studies have characterized CAF signatures based on a limited set of markers, our study extends these findings by identifying a distinct PHLDA1-positive CAF subtype that is significantly associated with poor prognosis and tumor-stroma interactions." (PMID 40688078, 2025).
tumor (continued). "Translating these findings to CAF biology suggests that integrin–mTOR inhibitors may synergize with PHLDA1‐targeted approaches to normalize the stroma and enhance anti‐tumor immunity." (PMID 40688078, 2025). "Furthermore, PHLDA1 knockdown in CAFs significantly impaired tumor cell proliferation and migration." (PMID 40688078, 2025). "The consequences of this regulation could be dual, either promoting tumor progression or suppressing it, similar to the role of PHLDA1 described in tumors." (PMID 39630301, 2025). "In addition to molecular targeting of PHLDA1, recent bioengineering platforms offer promising avenues to overcome stromal barriers and reshape the tumor microenvironment." (PMID 40688078, 2025). "Key differentially expressed genes included PTGS2 (pro/antitumor), FOSL1, TNFRSF9, IL1B, DIO2, and PHLDA1 (antitumor), along with under-expressed genes with pro-tumor effects that may inhibit proliferation." (PMID 39409923, 2024). "This suggests that combining 4SC-202 and lapatinib may limit the growth of lapatinib-resistant HER2+ tumours by re-sensitising cancer cells to lapatinib through the re-expression of PHLDA1." (PMID 37047202, 2023). "Thus, the combination of ERK pathway inhibitors with drugs such as bortezomib that retain PHLDA1/2 expression in cancer would be a potential strategy to achieve efficient tumor regression with fewer side effects." (PMID 35831322, 2022). "Moreover, PHLDA1 is not only a tumor suppressor, but also a new targeted therapy to re-sensitize drug-resistant cancer cells." (PMID 36092920, 2022). "PHLDA1 was first identified as a modulator of T cell apoptosis more than 20 years ago, and since then, there were several reports revealed that PHLDA1 might have both pro- and anti-apoptotic functions depending on the cells and tumor context 6-11,17." (PMID 34405011, 2021). "Taken together, these reports demonstrated that PHLDA1 might have different functions in the context of different tumor tissues and cell types." (PMID 34405011, 2021). "Therefore, further studies of direct regulation between high ECM stiffness and miRNAs or PHLDA1 need to be broaden and we will expound more upon the function of miR-3682-3p in different tumor microenvironment." (PMID 33033502, 2020). "A xenograft tumour assay was performed to explore the role of PHLDA1 in vivo as well." (PMID 31189920, 2019). "However, in oral squamous cell carcinoma, the expression of PHLDA1 was very low and acted as a tumor suppressor." (PMID 30410722, 2018). "So, PHLDA1 acts as an oncogene or a suppressor in tumor depending on their background." (PMID 30410722, 2018). "It remains to be determined whether initial PHLDA1 expression in a tumor influences the response to treatment and whether this can be used to identify patients who are likely to develop resistance." (PMID 29490281, 2018). "Of these, DUSP4 and DUSP6, PHLDA1 and Sprouty 4 are characterized by tumor suppressing properties." (PMID 22427941, 2012). "In our study, elevated PHLDA1 expression was associated with the activation of protumorigenic pathways such as EMT, KRAS, and TGF-β, suggesting that it may contribute to the regulation of tumor cell transformation, invasion, and migration." (PMID 40688078, 2025). "However, HDAC2 can be reactivated, repressing tumor-suppressor gene expression, such as PHLDA1." (PMID 41224124, 2025). "PHLDA1 may have a role in a variety of biological processes, including cell differentiation, cell proliferation, cell death, cancer metastasis, and epithelial–mesenchymal transition; it also has tumor stem cell properties." (PMID 38921000, 2024). "However, regardless of whether their regulatory functions are consistent, the functions of PHLDA1/2 in the tumor immunoregulation of PAAD are very active." (PMID 36142223, 2022).
tumor (continued). "However, in many species like rat, rabbit and human, PHLDA1 was a needy role for Fas/FasL expression, and inhibited Akt pathway in various tumor behaviors such as apoptosis, autophagy, epithelial to mesenchymal transition (EMT) and endoplasmic reticulum (ER) stress 30-33, 35, 39-41." (PMID 33033502, 2020). "Notably, miR-526b-5p inhibitor not only facilitated cell proliferation, decreased cell apoptosis, as well as promoted the abilities of migration, invasion, and colony formation but also abrogated the tumor suppressive effect induced by circ0085539 and PHLDA1 silencing in OS cells." (PMID 32983961, 2020). "PHLDA1 could function as an oncogene or a tumor suppressor gene in cancers." (PMID 30410722, 2018). "We also demonstrated that PHLDA1 overexpression could inhibit Akt activation, results in reduced cell proliferation and cell motility consistent with its putative function as an Akt pathway inhibitor and suggestive of a candidate tumor suppressor function." (PMID 25238247, 2014). "Unsurprisingly, a notable pattern of elevated PHLDA1, PHLDA2 and PHLDA3 expression in tumor tissues was observed in both GSE40435 and GSE53757 (all p < 0.05)." (PMID 39033192, 2024). "The results show that the roles of PHLDA1 and PHLDA2 in PAAD immune regulation were opposite, which indicated that the roles of the PHLDA family members in PAAD tumor immune regulation are diverse and complex." (PMID 36142223, 2022). "The dot plots showed the proportion of cells expressing tumor stemness-related gene markers (CD44 and MKI67) and key DEeRNAs (PHLDA1 and RASD1) and their scaled relative expression level in 12 cell clusters." (PMID 36092920, 2022). "It has been shown that the PH domain of the PHLDA1 protein can inhibit Akt function by binding to phosphatidylinositol (PIP), which can inhibit tumor progression." (PMID 36142223, 2022). "Based on Oncomine database, we identified that expression of CCR1, CD3D, MAZ, PHLDA1, and RASD1 was higher in tumor than that in normal tissue at the pan-cancer level." (PMID 36092920, 2022). "Top upregulated master regulators in the tumor, as compared to the parent cells, include ZEB2 and PHLDA1; while top downregulated master regulators include AR, AHR, and ITGA6." (PMID 33808801, 2021). "According to database, we had understood that PHLDA1 was low-expressed in HCC tissues and related to tumor grades and differentiation." (PMID 33033502, 2020). "The role of PHLDA1 in apoptosis and autophagy is interconnected but not uniform, depending on the type of tumor and, in some instances, even the cell line." (PMID 39630301, 2025). "We further investigated the expression of key DEeRNAs between tumor and normal samples among different cancer types and identified that the expression level of CCR1, CD3D, PHLDA1, and RASD1 was significantly up-regulated in tumor tissue, as compared with normal tissue." (PMID 36092920, 2022). "ERK-induced PHLDA1/2 upregulation in pre-treated cancer cells inhibits AKT, which may somewhat suppress tumor cell survival and progression in patients." (PMID 35831322, 2022). "The mRNA level of CXCL12, F3, PHLDA1, and ZEB2 was upregulated in the tumor samples." (PMID 33808801, 2021). "We also identify a compact set of gene changes upon ErbB2 inhibition and demonstrate strong overlap with EGFR-driven cancers and further identify PHLDA1 as a novel negative feedback inhibitor and candidate tumor suppressor in ErbB2-dependent cancers." (PMID 25238247, 2014). "Comparing the ErbB2 positive with ErbB2 negative samples, PHLDA1 was found to be significantly less expressed in ErbB2 negative tumor slides (p<0.05)." (PMID 25238247, 2014).
tumor (continued). "These HLA-A24 ligands were possibly overexpressed in tumor samples and were therefore chosen as nonmutated TAA candidates of CRC111, which comprised peptides encoded by the KLK8, DEFA3, STRIP2, MMP1, FSCN1, TBX15, and PHLDA1 genes." (PMID 34185709, 2021). "To explore the pathway that miR-3682-3p effected on division and apoptosis, we examined protein level of PHLDA1, Fas (or called TNF receptor superfamily member 6) and cyclin dependent kinase inhibitor 1A (CDKN1A, also known as P21) in vivo by testing transplanted tumor nodules." (PMID 33033502, 2020). "In conclusion, there was no final verdict of the values whether PHLDA1 played a positive or negative status in HCC with the high-expression in tumor specimens." (PMID 33033502, 2020). "Five genes with tumor suppressing properties, i.e. SPRY4 (Sprouty homolog 4), DUSP4 and DUSP6 (dual-specificity phosphatases 4 and 6), LRIG1 (Leucine-rich repeats and Ig-like domains 1) and PHLDA1 (Pleckstrin homology-like domain family A, member 1), were upregulated by KGF (1.5–2.1 fold)." (PMID 22427941, 2012). "In addition, reduced expression or inactivation of pleckstrin homology-like domain family A member 1 (PHLDA1)—a critical negative regulator of PI3K–AKT signaling—can unleash AKT activity and promote a resistant phenotype, a mechanism functionally validated in multiple RTK-driven tumor models." (PMID 41514604, 2025). "IMR90 cells, on the other hand, seemed to be impacted by a different panel of genes, BTG2, FBXW7, NDUFAF2, PHLDA1, and DMD, whose knockdown did not have a significant impact in the two tumor cell lines, suggesting cell line-specific effects." (PMID 24009623, 2013). "However, there was no final conclusion that PHLDA1 played a positive or negative status in HCC, for inconsistent researches were published during the 10 years, which discussed the multiple function of PHLDA1 in same kind of tumor." (PMID 33033502, 2020).
cancer (34 papers, 2014 to 2025). A tumor composed of atypical neoplastic, often pleomorphic cells that invade other tissues. "PHLDA1 functions were implicated in a vast number of pathophysiological conditions such as cancer, ischemia/reperfusion injury, and lipid disorders." (PMID 39630301, 2025). "Since these pleckstrins are highly expressed in some cancers, the R2 genomics platform was utilized to find genes associated with PHLDA1, PHLDA2, and PHLDA3." (PMID 38921000, 2024). "In the interaction and correlation network, PHLDA1 was also related to cancer-associated fibroblasts (R = 0.67; p < 0.001) and CCR (R = 0.53; p < 0.001)." (PMID 36092920, 2022). "The apoptotic activation and apoptotic suppression capacity caused by PHLDA1 simultaneously existed in the cancer cell." (PMID 32983961, 2020). "The authors also reported that PHLDA1 expression levels are correlated with less susceptibility of cancer cells developing resistance to RTKi therapies." (PMID 32429563, 2020). "The opposing views thus suggest that PHLDA1 shows different roles in different cell types and could cause different apoptosis susceptibility of different cancer cells." (PMID 32983961, 2020). "Further in vivo studies are warranted using animal models that will clarify the PHLDA1 role in normal and cancer cells." (PMID 39630301, 2025). "Last, the single-cell RNA sequencing data revealed abundant PHLDA1 expression in cancer stem cells in Ewing sarcoma." (PMID 39630301, 2025). "PHLDA1 (pleckstrin homology-like domain, family A, member 1) is a multifunctional protein involved in pathophysiological conditions such as cancer." (PMID 41430389, 2025). "The role of PHLDA1 as a prognostic marker of cancer emerges, as well as its role in drug response and resistance." (PMID 39630301, 2025). "A 7-gene mCAF-associated risk model was constructed using advanced machine learning algorithms, and the biological significance of PHLDA1 was validated through co-culture experiments and pan-cancer analyses." (PMID 40688078, 2025). "Based on the data gathered above, it can be concluded that PHLDA1 is a multifaceted protein with context-dependent functions in cancer." (PMID 38495105, 2024). "We conducted a comprehensive analysis using the R2 platform to detect genes associated with PHLDA1, PHLDA2, and PHLDA3 expression in particular cancers." (PMID 38921000, 2024). "All four cancer types considered in our study matched 222 genes with a positive correlation to PHLDA1 (hereafter referred to as “PHLDA1-correlated gene cluster”)." (PMID 38921000, 2024). "In comparison to PHLDA1, fewer genes associated positively with PHLDA2 in each type of cancer, and 188 genes (referred to as the “PHLDA2-correlated gene cluster” above) were common for all four tumors studied." (PMID 38921000, 2024). "Knocking down of Pleckstrin Homology-Like Domain, family A, member 1 (PHLDA1) promoting the sensitivity of cancer cells to CDDP." (PMID 37291676, 2023). "The downregulation of Pleckstrin Homology-Like Domain family A member 1 (PHLDA1) expression mediates resistance to targeted therapies in receptor tyrosine kinase-driven cancers." (PMID 37047202, 2023). "Knockdown of PHLDA1 in different types of cancer cells promotes Akt activation, whereas overexpression of PHLDA1 reduced its activation." (PMID 37225844, 2023). "PHLDA1 negatively regulates Akt in the context of FGFR2, whereas loss of PHLDA1 expression contributes to cancer cell survival and FGFRi resistance due to reactivation of Akt." (PMID 37225844, 2023). "PHLDA1 is a protein-coding gene expressed in various mammalian tissues and plays key roles in regulating different biological processes in cancer, including cell cycle progression, proliferation, and tumorigenesis." (PMID 37749575, 2023). "The restoration and maintenance of PHLDA1 levels in cancer cells thus constitutes a potential strategy to circumvent resistance to inhibitors of receptor tyrosine kinases." (PMID 37047202, 2023).